IL6 (interleukin 6)
Diseases named in the same sentence as IL6 in open-access papers (continued):
Sharing a sentence is not in itself a finding about the gene and the disease.
cancer (continued). "Interleukin-6 (IL-6) is a multifunctional pro-inflammatory interleukin involved in many types of cancer." (PMID 27852059, 2016). "The ultimate goal for cancer immunological study is to achieve a treatment outcome where cancer-promoting cytokine signaling (TNFα, IL-1, IL-6, IL-17 and IL-23) is blocked to slow down cancer cell growth and reduce their survival and therapy resistance." (PMID 31051015, 2016). "Emerging evidence suggests that Interleukin (IL)-6 signaling correlates with the survival of cancer stem cells and resistance to therapy." (PMID 26287605, 2015). "The purpose of the study was to evaluate the role of PCT and IL-6 as biomarkers of cancer and its progression in a large cohort of patients." (PMID 26148092, 2015). "Cytokines, especially interleukin-6 (IL-6) family, are now recognized as important mediators linking inflammation and cancer, and are potential therapeutic and preventive targets as well as prognostic factors." (PMID 26313265, 2015). "Fourthly, nearly all involved studies had circulating IL-6 measured only once, which cannot reflect its long-term level in the development of cancer." (PMID 26096712, 2015). "On the other hand, adipokines including inflammatory cytokines such as interleukin-6 (IL-6) and tumour necrosis factor-α (TNF-α) as well as Zinc-α2-glycoprotein (ZAG) have also been associated with weight and fat loss in cancer." (PMID 26508820, 2015). "Aberrant IL-6-Jak-STAT3 signaling in cancer cells has also emerged as an important mechanism for cancer initiation, development and progression." (PMID 26501341, 2015). "Our results revealed that in HDC−/− mice, there was marked induction by OVA of a number of MC-derived proinflammatory cytokines, including several key cancer-promoting cytokines such as IL-1β and IL-6 and their downstream effector cytokine IL-17a." (PMID 26429861, 2015). "The ADSC-enhanced cell growth of cancer cells was significantly suppressed by IL-6–neutralized antibodies." (PMID 25797257, 2015). "Cancer cells can also produce IL-6, which has a cell-proliferative effect, triggering the differentiation of megakaryocytes to platelets in the bone marrow." (PMID 25950176, 2015). "Although cachectic cytokines, such as TNF-α and IL-6, are elevated in the sera of cancer patients, clinical trials with one-target inhibitors have proven ineffective." (PMID 25972815, 2015). "NF-κB can also influence angiogenesis by regulating the expression of cytokines such as interleukin-6 (IL-6) and interleukin-8 (IL-8), as shown in cancer cell models." (PMID 25705690, 2015). "NF-κB, one of these DNA-binding proteins, has been identified as a potential molecular bridge between inflammation and cancer, and can induce proinflammatory cytokines such as IL-1, IL-6 and TNF-α." (PMID 25889203, 2015). "Constitutive activation of IL-6/STAT3 signaling has been detected in a wide variety of human cancers and is considered as an important factor for cancer initiation, development, and progression." (PMID 26417930, 2015). "BMI influences cancers by releasing several inflammatory mediators, such as tumor necrosis factor alpha, interleukin-6, and prostaglandin E2." (PMID 25963193, 2015). "Meanwhile, IL-6 is an important factor for the synthesis of acute phase proteins, whose serum level is increased in acute and chronic inflammatory diseases such as cancer." (PMID 25821823, 2015). "Augmented proliferation of the cancer cells was reduced to values characterizing the effect of young HPMCs by the neutralization of IL-6." (PMID 26284488, 2015). "More recently, several studies have shown that IL-6 is also expressed in the cytoplasm of different cancer cells." (PMID 26148092, 2015). "The median IL-6 level in the control group was significantly lower than in patients with low stages of cancer or advanced stage IV cancer (0 pg/ml vs 7.376 pg/ml and 9.635 pg/ml, respectively, p<0.0001)." (PMID 26148092, 2015).
cancer (continued). "In conclusion, we showed that high expression of IL-6 in cancer cells predict poor response to chemoradiotherapy and unfavorable prognosis in patients with OSCC." (PMID 25761055, 2015). "The MB-downregulated genes include cancer-associated cytokines/chemokines (e.g. CXCL1, CXCL2, CXCL3, CXCL14, IL1A, IL1B, IL6, IL8) and matrix metalloproteinases (MMP1,MMP9)." (PMID 25642713, 2015). "The increasing evidence regarding the molecular biology of IL-6 and its interrelations with human cancer cells as well as their microenvironments have led to the development of novel antibody-based therapies." (PMID 25658637, 2015). "To determine the contribution of IL-6 in mediating the ADSC-enhanced malignant characteristics of cancer cells, we utilized antibody to neutralize the function of IL-6." (PMID 25797257, 2015). "These cells can be generated in the bone marrow in response to factors such as IL-6, GM-CSF, IL-1β, TNFα and have been shown to contribute to cancer immune evasion by suppressing T cell functions and promoting activation and expansion of Foxp3+ Tregs cells." (PMID 26109431, 2015). "Currently, targeted anti-IL-6 antibody therapy has been successfully applied in several clinical trials and found to be well tolerated in cancer patients." (PMID 26096712, 2015). "For example, an inkjet-printed gold nanoparticles (AuNPs) array immunosensor was fabricated for the multiple detection of the cancer biomarker interleukin-6 (IL-6) in serum." (PMID 26343676, 2015). "Several cytokines such as interleukin-6 (IL-6) and interleukin-8 (IL-8) are known to be involved in angiogenesis and metastasis in different types of cancer." (PMID 26576504, 2015). "Increased serum levels of IL-6 have been observed in a variety of cancers and predict an adverse outcome." (PMID 25797257, 2015). "For the purpose of evaluating the correlation between immunoreactivity for IL-6 in cancer cells and the clinical outcomes of the patients with OSCC, the survival rates were calculated by the Kaplan-Meier method." (PMID 25761055, 2015). "Many reports have shown that in several cancers, IL-6 performs important functions in cancer progression, including proliferation, migration, and angiogenesis." (PMID 26690480, 2015). "This group proposed that targeting IL6/STAT3 to inhibit cancer stem cell function has important therapy implications for the treatment of HCC." (PMID 26074923, 2015). "On the other hand, ROS can stimulate the JAK2/STAT3 pathway through the induction of a positive ROS/IL-6/JAK2/STAT3 feedback during starvation-induced autophagy of cancer cells." (PMID 26106584, 2015). "A high number of stromal IL-6+ cells was previously shown to be correlated with poor disease-specific survival in an overlapping patient cohort and other types of cancer." (PMID 25889974, 2015). "Based on these data, the inhibition of the IL-6/IL-6 receptor interaction with specific antibodies has been proposed as a support cancer therapy." (PMID 25881039, 2015). "On the other hand, neutrophilia was triggered by cancer-related inflammatory factors, including tumor necrosis factor-alpha, interleukin-6, granulocyte colony stimulating factor, and myeloid growth factors." (PMID 25885254, 2015). "Cancer cachexia is triggered by increased systemic inflammation, where pro-inflammatory cytokines (e.g. IL-6) play a major role." (PMID 25460504, 2015). "Serum TNF-α and IL-6 in the severe cancer group were higher than those in control, whereas serum IL-1β leveled off in all groups." (PMID 25797259, 2015). "In PCa and several other cancers, elevated serum IL-6 levels correlate with a poor prognostic outcome for patients." (PMID 26198641, 2015). "Both IL-8 and IL-6 are involved in the IR inflammatory response and enhance cancer cell invasiveness." (PMID 26569225, 2015). "Neutrophils treated with a2NTD (a2Neuɸ) showed increased secretion of IL-1RA, IL-10, CCL-2 and IL-6 that are important mediators in cancer related inflammation." (PMID 26460736, 2015).
cancer (continued). "These cytokines, including Interleukin-6 (IL-6), have been shown to foster a microenvironment conducive to the progression of various types of cancer." (PMID 26231887, 2015). "The importance of the IL-6/Stat3 signaling in cancer and cancer stem cells has been well documented." (PMID 26376676, 2015). "IL-6 was also higher in cancer samples with HPV other than 16 and 18, however the differences were not statistically significant (data not shown)." (PMID 25810759, 2015). "For example, leucocytes from cancer patients with post-treatment fatigue showed increased expression from both IL-1β and IL-6 genes." (PMID 26469939, 2015). "Signaling mediated via the interleukin-6 (IL-6)/interleukin-6 receptor (IL-6R) plays a pivotal role during immune responses and in cancer." (PMID 26091352, 2015). "High levels of gene expression of IL6 receptor, GP130, in luminal A and B warrant further studies of paracrine roles of IL6 in luminal cancer." (PMID 26173622, 2015). "As a multifactorial cytokine, interleukin-6 (IL-6) is widely believed to play a role in the progression and severity of many forms of cancer." (PMID 26096712, 2015). "This possible up-regulation of 2 important tumor suppressors, p16 and miR-146b-5p, and the repression of IL-6, opens new avenues for anti-cancer drug development through targeting stromal fibroblasts and their paracrine effects." (PMID 26338965, 2015). "Recently, it was shown that TERT interact with NFκB and co-activate the expression of several genes, including cytokines, such as IL-6 and TNFα, that are critical for inflammatory reactions and cancer progression." (PMID 26298771, 2015). "Cancer cells exposed to IL-6 or which secrete the cytokine as an autocrine factor, show malignant features, such as an enhanced capacity to invade the extracellular matrix and an increased drug resistance." (PMID 25881039, 2015). "Since IL-6 is secreted from stromal cells derived from other organs, IL-6 is one of general factors that stimulate cancer development." (PMID 25785838, 2015). "IL-6 expression of the low expression group was scattered in the cancer cells whereas almost all the cancer cells expressed IL-6 in the high expression group." (PMID 25761055, 2015). "IL-6 is a pleiotropic cytokine, which plays a role in hematopoiesis, regeneration, and the progression and development of cancer." (PMID 26087456, 2015). "A correlation between plasma IL-6, ageing/frailty and even with mortality had previously been consistently observed in numerous studies on general (non-cancer) geriatric populations." (PMID 25989735, 2015). "While contributing to the follicle development in normal ovaries and the regulation of chronic inflammation, IL-6 can be involved in the provision of a cellular microenvironment beneficial to cancer cell growth, proliferation, migration and survival." (PMID 26282935, 2015). "In fact, we have recently discovered that high leptin levels stimulate the secretion of other cytokines (e.g., IL-6) both from cancer cells and from other cell types present in the ascites (e.g., macrophages; manuscript in preparation)." (PMID 26053184, 2015). "The experiments revealed that the mediators of each aspect of cancer cell behavior are diversified: proliferation was driven by IL-6, migration by CXCL8 and CCL2, invasion by IL-6, MMP-3 and uPA, and EMT by TGF-β1." (PMID 26284488, 2015). "In particular, studies have shown that immune cells express high levels of IL-6 during the cancer progression." (PMID 26286584, 2015). "The cytokine interleukin 6 (IL-6) is produced by macrophages at sites of inflammation, especially acute inflammation, which occurs in cancer tumors during chemotherapy." (PMID 26016502, 2015). "Future research is required to clarify the mechanism and study the role of IL-6-pretreated hUC-MSCs in other types of cancer." (PMID 25483835, 2015).
cancer (continued). "Many studies have demonstrated that in response to paclitaxel administration, cancer cells up-regulate inflammatory mediators such as IL-1β, IL-6, IL-8, and VEGF-A, which also facilitate angiogenic activity." (PMID 26015406, 2015). "IL-6 is an important proinflammatory cytokine that plays a key role in the development of cancer and closely correlates with CRP levels." (PMID 26084991, 2015). "Seven of 9 study groups provided circulating IL-6 in cancer patients, and 1 study group respectively in healthy controls and in combined patients and controls." (PMID 26096712, 2015). "Signal transducer and activator of transcription 3 (STAT3) can also promote IL-6 production in serum-starved cancer cells." (PMID 26087456, 2015). "For instance, il1b, which promotes early cancer angiogenesis, was significantly upregulated while anti-tumor cytokines, il4, il6, il8, il10, il12, and tnfa, all showed significant downregulation." (PMID 25828472, 2015). "S100A9-mediated increase of IL-6 expression was partly through the cross-talk between cancer and myeloid cells." (PMID 26315114, 2015). "The IL-6 pathway maintains CSCs/PCSLCs and regulates their plasticity required for cancer evolution, particularly under therapeutic pressure." (PMID 26593949, 2015). "Conversely, treatment of cancer cells with 1 ng of recombinant IL-6 mimicked CAF chemoprotection, although less efficiently than whole CAF-CM, since a residual fraction of PARP remained cleaved (Fig6F)." (PMID 25834145, 2015). "As expected, large amounts of IL-6 were secreted by macrophages co-cultured with apoptotic MCF-7 cancer cells, accompanied by the phosphorylation of STAT3 and the upregulation of the mRNA levels of TGF-β1 and HIF-1α." (PMID 26016502, 2015). "To identify what downstream signals in cancer cells respond to IL-6, we looked at JAK2/STAT3 pathway." (PMID 25797257, 2015). "As suggested by both our transcriptome and protein analyses, the link between TLR9/NF-κB and STAT3 signaling likely relies on IL-6 secretion by cancer cells." (PMID 26046794, 2015). "IL-6 is secreted by a wide array of immune, endothelial as well as cancer cells in an inducible manner." (PMID 25868978, 2015). "The inflammation amplifier reflect genes associated with cancer development, and several genes from the amplifiers were found up-regulated in necrotic tumors, like PTGS2, IL6, SERPINE1 and SOD2." (PMID 26485755, 2015). "We have recently showed that endothelial cell-secreted IL-6 enhances the tumorigenic potential of cancer stem cells." (PMID 26287605, 2015). "Above results suggest that ADSC-derived IL-6 played a critical role in activating malignant characteristics of cancer cells in cancer/ADSC interaction." (PMID 25797257, 2015). "Upon closer inspection of the genes, genes like interleukin-6 (IL6), which are upregulated in other cancers were seen to be downregulated upon luteolin treatment." (PMID 26517526, 2015). "Chemotherapy is known to increase concentrations of proinflammatory cytokines such as TNF-α, IL-6, and IL-1β in cancer patients." (PMID 25945105, 2015). "In contrast, the co-culture supernatants showed high IL-6 and IL-8 levels similar to cancer cells alone." (PMID 26317041, 2015). "In most cancers, it is possible to isolate a small subset of cancer cells that express EMT and stemness markers; this subset, termed cancer-initiating cells (CICs), adapt and respond to environmental stimuli (e.g., IL-6, EGF) to invade and metastasize." (PMID 26053184, 2015). "Several studies have highlighted the effect of the IL-6/JAK/STAT signaling pathway on cancer initiation and progression." (PMID 24901008, 2014). "The positive feedback loop that produces IL6 is important for cancer cells from diverse developmental lineages." (PMID 24709904, 2014). "Both the IL6 neutralizing antibody and bevacizumab produced significant reduction of cancer cell proliferation." (PMID 24885802, 2014).
cancer (continued). "Increased serum HP is a very frequent report in cancer, and is assumed as a marker of inflammation and tissue damage, mainly triggered by interleukins such as IL-6 and TNF-α." (PMID 24497876, 2014). "In a clinical trial of IL-6 in patients with malignancies, IL-6 was found to induce fever, chills, and general malaise." (PMID 24872899, 2014). "We found that levels of IL-6, IL-8, and IL-10 were significantly higher (up to 3 times) in cancer patients than in healthy individuals." (PMID 24849506, 2014). "The pathological role of IL-6 in cancer has also been validated with successful treatment of certain diseases with drugs inhibiting IL-6 signaling." (PMID 24670367, 2014). "MiRNAs can notably regulate whole biological pathways; for example, miR-181 controls mouse hematopoiesis, miR-608 targets two inflammation-related transcripts, CDC42 and IL6 and miR-221 controls multiple cancer pathways." (PMID 24574962, 2014). "Interleukin 6, for instance, in addition to its main function in immunological processes, influences growth and differentiation and plays a role in cancer." (PMID 25102311, 2014). "Recent studies have provided direct evidence that MSCs are recruited in TME by a broad range of soluble factors which are secreted by cancer cells and CSCs, including IL-6, VEGF and bFGF, CCL2, SDF-1α, and HMGB1." (PMID 25136593, 2014). "Unfortunately, increased levels of interleukin-6 and carcinoembryonic antigen, and computed tomography scan results indicated cancer progression." (PMID 24885608, 2014). "FN-β1 integrin signal was also found to synergistically enhance STAT3 activation induced by EGF and IL-6 in breast or other cancer cells." (PMID 25327561, 2014). "In our clinical and in vivo studies, we showed the usefulness of serum IL-6 as a surrogate marker for evaluating the prognosis and efficacy of anti-IL-6 receptor antibody as a mediator of cancer cachexia." (PMID 25010770, 2014). "A comprehensive multiplex assay of the supernatant of cancer cells co-cultured with human vascular endothelial cells and fibroblasts indicated significantly higher interleukin-6 (IL6) levels than those in the supernatant of monocultured cells." (PMID 24885802, 2014). "Currently, several monoclonal antibodies (mAbs) and mAb mixtures against IL-6 and IL-6R (in preclinical models) are being developed with encouraging results in cancer cell lines and animal models." (PMID 24670367, 2014). "Studies on the stimulation of CD40 present on cancer cell lines in the bladder, pancreas, or breast through the recombinant CD40L have shown increased expression of ICAM and Fas by cancer cells and the production of IL-6, IL-8, GROα, GM-CSF, and TNF-α." (PMID 25117071, 2014). "We and others have established the IL-6 driven, colon 26 (C26) carcinoma cachexia mouse model to study cancer cachexia." (PMID 24782788, 2014). "Families of growth factors or cytokines, such as fibroblast growth factor or interleukin 6, respectively, are known to play a role in maintaining and/or expanding cancer stem-like populations through autocrine or paracrine signaling." (PMID 25358638, 2014). "IL-6–activated STAT3 is crucial for survival of several types of cancer cell, including multiple myeloma, a plasmacytic B-cell malignancy." (PMID 25344679, 2014). "It has been reported that IL-6 stimulates the directional migration and invasion of human cancer cells." (PMID 24398980, 2014). "In this context, JAG1 seems to play a central role in linking various pathways, involving well-established cancer-related molecules such as Notch3, interleukin-6 (IL-6), carbonic anhydrase IX (CAIX), and NF-κB." (PMID 25309874, 2014). "Cancer cachexia is regulated by proinflammatory cytokines such as interleukin-6 (IL-6), monocyte chemoattractant protein-1 (MCP-1), and tumor necrosis factor-α (TNF-α)." (PMID 24963216, 2014). "Over-expression of STAT3 or treatment with IL-6 not only increased anoikis resistance, but also protected the cancer cells from PL-induced anoikis." (PMID 25216522, 2014).